GPATCH3 (G-patch domain containing 3)
Description:
Involved in transcriptional regulation. It is able to activate transcription from the CXCR4 promoter and therefore it might control neural crest cell migration involved in ocular and craniofacial development. Is a negative regulator of immune antiviral response, acting via down-regulation of RIG-I-like receptors signaling and inhibition of type I interferon production. The control mechanism involves interaction with mitochondrial MAVS and inhibition of MAVS assembly with downstream proteins implicated in antiviral response, such as TBK1 and TRAF6.
Synonyms: GPATC3; FLJ12455
Tractability: PROTAC: ubiquitination databases record sites on it.
Gene: Protein-coding gene on chromosome 1 (26,890,488 to 26,900,467, reverse strand). Ensembl gene ENSG00000198746.
Subcellular location: Nucleus; Cytoplasm
Subcellular location (Human Protein Atlas): Nucleoplasm; Cytosol
Gene Ontology:
Molecular function: protein binding; nucleic acid binding
Biological process: negative regulation of RIG-I signaling pathway; negative regulation of type I interferon production; positive regulation of DNA-templated transcription
Cellular component: cytoplasm; cytosol; nucleoplasm; nucleus
Genetic constraint (gnomAD): Loss-of-function variants: 46 observed, 58.28 expected, observed/expected ratio (o/e) 0.79, 90% interval 0.62 to 1.01. The upper end of that interval is the gene's LOEUF score, 1.01, which puts it in group 4 of 6, group 1 being the genes least tolerant of losing a copy. Missense variants: 680 observed, 729.53 expected, observed/expected ratio (o/e) 0.93, 90% interval 0.87 to 0.99. Synonymous variants: 280 observed, 289.91 expected, observed/expected ratio (o/e) 0.97, 90% interval 0.88 to 1.07.
Homologues: Orthologues: chimpanzee GPATCH3 (99% identical), macaque GPATCH3 (97% identical), dog GPATCH3 (89% identical), pig GPATCH3 (87% identical), guinea pig GPATCH3 (85% identical), mouse Gpatch3 (85% identical), rat Gpatch3 (84% identical), rabbit GPATCH3 (74% identical), zebrafish gpatch3 (54% identical), tropical clawed frog gpn2 (38% identical), Caenorhabditis elegans K07B1.7 (34% identical).
Diseases named in the same sentence as GPATCH3 in open-access papers:
GPATCH3 is named in the same sentence as 13 diseases in open-access papers, as found by Europe PMC text mining. Sharing a sentence is not in itself a finding about the gene and the disease. The quoted sentences say what the papers report.
congenital glaucoma (2 papers, 2017 to 2019). "Our results suggest the existence of remarkable genetic heterogeneity in congenital glaucoma and provide evidence for the role of GPATCH3 in this disease." (PMID 28397860, 2017).
glaucoma (1 paper, 2017). Increased pressure in the eyeball due to obstruction of the outflow of aqueous humor. "In an effort to assess the involvement of GPATCH3 in ocular development and glaucoma, we studied the expression and function of the zebrafish orthologue in early embryos." (PMID 28397860, 2017). "Western blot and immunohistochemistry revealed consistent expression of GPATCH3 in glaucoma-related adult human ocular tissues." (PMID 28397860, 2017). "The GPATCH3 protein was detected in human tissues relevant to glaucoma (e.g., ciliary body)." (PMID 28397860, 2017).
glioma (1 paper, 2025). A benign or malignant brain and spinal cord tumor that arises from glial cells (astrocytes, oligodendrocytes, ependymal cells). "Kaplan–Meier curves demonstrated that high GPATCH3 expression is associated with reduced overall survival in multiple cancer types, including lower-grade glioma (LGG), liver hepatocellular carcinoma (LIHC), and prostate adenocarcinoma (PRAD)." (PMID 40861452, 2025). "Our pan-cancer analyses revealed that GPATCH3 is upregulated in various tumor types and is significantly correlated with poor patient survival in glioma, liver, and prostate cancers." (PMID 40861452, 2025).
iridocorneal endothelial syndrome (1 paper, 2017). "The second proband (MOC-F5), diagnosed with secondary glaucoma and iridocorneal endothelial syndrome, presented three rare non-coding GPATCH3 variants (c.-298_−295delGAGG, c.*263C > T and c.*274C > T) with frequencies equal to or less than 1%." (PMID 28397860, 2017).
microcephaly (1 paper, 2017). A congenital or acquired developmental disorder in which the circumference of the head is smaller than normal for the person's age and sex. "Gpatch3 morphants were classified into four abnormal phenotypic classes according to increasing degree of microphthalmia, microcephaly, pericardial edema and maldevelopment of cartilages present in pectoral fins, jaws and branchial arches." (PMID 28397860, 2017).
virus infection (1 paper, 2017). "Taken together, these date suggest that GPATCH3 interacts with VISA following viral infection and its physical binding to VISA is sufficient and necessary for the inhibitory function." (PMID 28414768, 2017). "Mechanistically, GPATCH3 was recruited to VISA in a viral infection dependent manner and the assembly of VISA/TRAF6/TBK1 signalosome was impaired in GPATCH3-overexpressing cells." (PMID 28414768, 2017). "Biochemically, GPATCH3 was recruited to VISA in a viral infection dependent manner where it disrupts the assembly of VISA/TRAF6/TBK1 complexes." (PMID 28414768, 2017). "In contrast, upon viral infection, the recruitment of TRAF6 and TBK1 to VISA was enhanced in GPATCH3 deficient cells." (PMID 28414768, 2017). "Consistently, the results showed that although GPATCH3 constitutively localized on mitochondria, it was recruited to VISA in a virus infection dependent manner." (PMID 28414768, 2017). "In this study, we further found that GPATCH3, a functionally uncharacterized protein, interacted with mitochondria-localized VISA upon virus infection and disrupted the assembly of VISA-signalosome." (PMID 28414768, 2017). "Intriguingly, the subcellular distribution of GPATCH3 did not change after virus infection." (PMID 28414768, 2017).
cancer (1 paper, 2025). A tumor composed of atypical neoplastic, often pleomorphic cells that invade other tissues. "Conversely, elevated GPATCH3 expression was associated with reduced infiltration of cytotoxic T cells and NK cells, alongside an enrichment of immunosuppressive populations such as MDSCs and CAFs across multiple cancer types." (PMID 40861452, 2025). "Here, we identify GPATCH3, a previously uncharacterized G-patch domain–containing protein, as a critical modulator of alternative splicing and immune regulation in cancer." (PMID 40861452, 2025). "Understanding these upstream controls may reveal new vulnerabilities in cancers with high GPATCH3 activity." (PMID 40861452, 2025). "Notably, GPATCH3 is significantly upregulated across multiple cancer types and correlates with adverse patient prognosis." (PMID 40861452, 2025). "Given the well-established role of immune cell infiltration in modulating antitumor immunity, we hypothesized that GPATCH3, a poorly characterized gene in cancer biology, might influence TME composition." (PMID 40861452, 2025). "Together, these data highlight GPATCH3 as a potential oncogenic factor that promotes tumor progression and may serve as a prognostic biomarker in certain cancers." (PMID 40861452, 2025). "Heatmap analyses revealed that GPATCH3 expression was broadly negatively correlated with chemokines such as CXCL5 and CXCL8, as well as immunostimulatory molecules including CD40LG and TNFSF15, in a pan-cancer context." (PMID 40861452, 2025).
infection (1 paper, 2017). The state of being infected such as from the introduction of a foreign agent such as serum, vaccine, antigenic substance or organism. "Consistently, knockdown of GPATCH3 markedly impaired replications of both SeV and VSV at all examined time points post infection." (PMID 28414768, 2017).
tumor (1 paper, 2025). "In functional assays, GPATCH3 depletion suppressed tumor growth in xenograft models, supporting its pro-tumorigenic role." (PMID 40861452, 2025). "In conclusion, our study establishes GPATCH3 as a previously unrecognized splicing regulator that mechanistically links spliceosome activity to tumor progression and immune modulation." (PMID 40861452, 2025). "Mechanistically, we show that GPATCH3 reprograms the tumor immune microenvironment by limiting cytotoxic immune cell infiltration while increasing immunosuppressive populations—a phenotype potentially linked to its splicing regulatory activity." (PMID 40861452, 2025). "In vitro and in vivo models, including GPATCH3-depleted cell lines and mouse xenografts, were used to assess its roles in tumor progression." (PMID 40861452, 2025). "Since immunosuppressive microenvironments often underlie resistance to checkpoint inhibitors, targeting GPATCH3 could potentially reprogram the immune landscape in favor of tumor clearance." (PMID 40861452, 2025). "Moreover, in vivo studies using different immunocompetent models would be valuable to elucidate how GPATCH3-driven splicing reprogramming affects immune cell composition and tumor–immune dynamics in a physiologically relevant setting." (PMID 40861452, 2025). "By modulating the splicing fidelity of key immune genes and altering their expression, GPATCH3 may facilitate immune escape and tumor progression." (PMID 40861452, 2025). "Furthermore, combining GPATCH3-targeted interventions with immune checkpoint blockade may synergistically enhance anti-tumor immunity." (PMID 40861452, 2025). "In addition, the tissue-specific roles of GPATCH3 in different tumor contexts, as well as its potential non-splicing functions, warrant further investigation." (PMID 40861452, 2025). "Notably, depletion of GPATCH3 led to significant upregulation of CXCL8, CCL5, LAG3, and PVRL2 —genes with well-established roles in immune cell recruitment, immune checkpoint signaling, and tumor–immune interactions." (PMID 40861452, 2025).
GPATCH3 also shares sentences with these, for which no sentence is quoted: anterior segment dysgenesis (1 paper); microphthalmia (1); prostate adenocarcinoma (1); prostate carcinoma (1).